TEX55 (testis expressed 55)
Synonyms: C3orf30; TSCPA; FLJ32859
Tractability: No criterion of Open Targets' tractability assessment is met for any kind of drug.
Gene: Protein-coding gene on chromosome 3 (119,146,151 to 119,160,042, forward strand). Ensembl gene ENSG00000163424.
Subcellular location: Nucleus; Cell projection, cilium, flagellum
Subcellular location (Human Protein Atlas): Nucleoplasm; Cytosol; Plasma membrane; Vesicles
Gene Ontology:
Molecular function: protein binding
Cellular component: sperm flagellum; nucleus; motile cilium
Genetic constraint (gnomAD): Loss-of-function variants: 29 observed, 43.27 expected, observed/expected ratio (o/e) 0.67, 90% interval 0.5 to 0.91. The upper end of that interval is the gene's LOEUF score, 0.91, which puts it in group 3 of 6, group 1 being the genes least tolerant of losing a copy. Missense variants: 627 observed, 659.6 expected, observed/expected ratio (o/e) 0.95, 90% interval 0.89 to 1.01. Synonymous variants: 228 observed, 243.32 expected, observed/expected ratio (o/e) 0.94, 90% interval 0.84 to 1.05.
Homologues: Orthologues: chimpanzee TEX55 (98% identical), macaque TEX55 (88% identical), mouse Tex55 (28% identical), rat Tex55 (27% identical). Paralogues in human: EFCAB10 (4% identical).